IFNG (interferon gamma)
Diseases named in the same sentence as IFNG in open-access papers (continued):
Sharing a sentence is not in itself a finding about the gene and the disease.
tumor (continued). "We evaluated the cytokine profiles of cells isolated from CRC tumor tissue and observed a time-dependent increase in the expression of the pro-inflammatory cytokines TNFα and IFNγ for all different treatment groups, whereas downregulation of anti-inflammatory cytokine IL10." (PMID 39164686, 2024). "Additionally, IFNG induces the apoptosis of tumor-specific T cells, compromising antitumor immunity." (PMID 38287309, 2024). "GZMA is a component of the interferon gamma (IFN-γ) signature, which has been demonstrated to serve as a predictor of response or non-response to anti-PD-1 therapy as part of an immune-related gene expression signature in ten distinct tumor types." (PMID 39596210, 2024). "Increased APCs, CD4+, CD8+, and interferon gamma indicate increased tumor vaccine effectiveness." (PMID 39682188, 2024). "Even if the levels of IFNγ are not very high in the sera of Hc-treated mice, the local intra-tumor IFNγ production by tumor-infiltrated CD4 Th1, CD8 cytotoxic T lymphocytes, and NK cells induced the generation of specific antitumor CTLs, responsible for tumor growth suppression." (PMID 38786612, 2024). "Moreover, tumour-infiltrating T cells in tumours treated with both RMC-4998 and RMC-4550 showed marked activation, proliferation, and expression of potential anti-tumour cytotoxic molecules, such as TNFα, IFNγ and Granzyme B." (PMID 39322643, 2024). "For example, Oh and colleagues used IFNγ as a sensitive measure of T-cell activity in order to assess the immune reactivity of advanced ovarian cancer patients to treatment with an autologous tumor cell vaccine." (PMID 38962090, 2024). "Furthermore, it enhances the production of tumor-specific interferon gamma (IFN-γ), further bolstering the anti-tumor immune response." (PMID 39267832, 2024). "These two constructs were tested for T cell-mediated killing of tumor cells and release of IFNγ." (PMID 38455046, 2024). "However, Th17 cells can also suppress tumor growth through CD8+ T cell activation in an interferon-gamma (IFN-γ)-dependent manner." (PMID 39683528, 2024). "Interestingly, the levels of IFNγ and TNFα, which are critical inflammatory cytokines, were also remarkably increased in tumor-bearing mice." (PMID 38690266, 2024). "Anti-tumor activity is dependent on a strong type 1 immunity and the release of IFNγ." (PMID 39267746, 2024). "Interestingly, the inflammatory angiostatic cytokines MIG, M-CSF, IL-10, and IFNγ were found to decrease in time-to-tumor progression." (PMID 39451257, 2024). "Moreover, NK cells were also involved in the reshaping of the tumor microenvironment into one responsive to ICB through sensitization therapy consisting of IFNγ, anti-IL-10 and TLR3 agonist poly-IC in subcutaneous tumor models." (PMID 39551601, 2024). "A positive association between circulating IL-8 levels and tumor mRNA expression of CXCL8, and an inverse correlation with tumor IFNγ and T cell signatures were also reported, demonstrating that circulating levels of IL-8 are reflective of changes in the tumor microenvironment." (PMID 38493133, 2024). "However, our current chronic HS diet treatment has shown a blunting of effector anti-tumor immune responses, as evidenced by the reduced expression of cytotoxic granzyme B and IFNγ in CD8+ and CD4+T cells." (PMID 38891044, 2024). "Finally, we report a reciprocal inhibition between TP63 and STAT1 at the transcription level, which determines anti-tumor immune response of SCC cells by regulating the IFNγ signaling." (PMID 38509096, 2024). "As we know, the cytokine IFNγ released by CD8+ T cells plays an important role in the tumor immune cycle, and could also increase the expression of PDL1, suggesting that persistent blockade of PDL1 might be needed in the clinical setting." (PMID 38263860, 2024). "IFNG is a major host response regulator of intracellular pathogen replication, as well as possessing antiviral, antibacterial, and anti-tumor properties." (PMID 38032489, 2024).
tumor (continued). "Three GAS-Luc2 reporter tumor cell lines endogenously expressing various immune checkpoints were engineered to produce quantifiable bioluminescence signal in the presence of an immune checkpoint inhibitor where activated T cells release IFNγ." (PMID 38893085, 2024). "This enhancement would lead to increased IFNγ secretion and enhanced ferroptosis in tumor cells." (PMID 38982045, 2024). "We also analyzed the relative expression of CD8+ T cell activation marker tumor necrosis factor alpha (TNFA) and interferon-gamma (IFNG) in tumor tissue, the average relative expression of TNFA and IFNG in FMD group is 1.45 times and 1.3 times higher than control group." (PMID 38918380, 2024). "Both GLUT1OE CARs demonstrated marked increases in tumor induced IL-2 and IFNγ secretion." (PMID 39370422, 2024). "Further, Bacteroides fragilis could improve CD3+T cells, NK cells, and IFNγ+CD8+ T cells in the tumor microenvironment to inhibit tumor growth." (PMID 39251538, 2024). "These three signatures consist of myeloid-focused cytokines (TNFa, GM-CSF, and IL-1b), chemokines (CCL3, CCL4, CCL5, CXCL9, and CXCL10), and an effector T-cell-derived cytokine (IFNg) and represent important aspects of a macrophage-based anti-tumor immune response." (PMID 39199551, 2024). "This dual-signaling activation hypothesis was confirmed using ELISA of IFNγ in the supernatant from the coculture of tumor cells and TILs after blockade of CSV and/or knockout of TRA." (PMID 39574893, 2024). "Conversely, soluble IFNγ can increase ICAM-1 expression but may also trigger cytokine toxicity depending on the tumor type." (PMID 39684867, 2024). "Increased LDs associated with reduced recruitment of IFNγ-secreting CD8+ T cells to tumor site could consequently avoid exposure of PD-L1 and PD-1 on tumor and CD8+ T cells." (PMID 38554152, 2024). "Compared to tumor-bearing controls, the percentage of IFNγ+ CD4+ Th1-prone cells after cryo-thermal therapy was higher than that of other CD4+ T subsets, although the increased percentages of Th1, Th17, Tfh prone CD4+ T cells were observed on day 7 after cryo-thermal therapy." (PMID 38827732, 2024). "Additionally, IFNγ modulates the tumor vasculature to improve T-cell trafficking and enhances T-cell recruitment by stimulating chemokine secretion." (PMID 39518094, 2024). "Thus, our results suggest that promotion of tumor antigen processing and presentation by zebularine is dependent on type I interferon signaling, with IFNγ further enhancing MHC-AgPPM expression." (PMID 38755254, 2024). "PD-L1 is expressed by tumor cells, epithelial cells, dendritic cells, macrophages, fibroblasts, and exhausted T cells, and its expression intensity is influenced by cytokines such as interferon-gamma (IFN-γ) and carcinogenic factors." (PMID 39200350, 2024). "Additionally, the tumor response to NK cell-produced interferon-gamma (IFN-γ) includes upregulated expression of PD-L1, which can contribute to an immunosuppressive environment." (PMID 39192980, 2024). "Additionally, lactate, another key metabolite produced by tumor cells due to their reliance on aerobic glycolysis, specifically suppresses NK cell cytotoxicity by inhibiting IFNγ production and NFAT activation." (PMID 39763648, 2024). "The precise mechanisms by which IFNγ impairs tumor growth are subject to active investigation." (PMID 38962090, 2024). "However, we observed a synergistic increase in serum IFNγ in the combination group consistent with the presence of cytotoxic anti‐tumour T‐cells in these allografted CT‐26 tumours." (PMID 38602256, 2024). "Only IFNγ remained higher on CD27+Ly6C+ γδ T cells in both tumor models." (PMID 38816652, 2024). "One plausible explanation for the high variability in PD-L1 in cancer tissues may be its dependence on the expression of IFNγ, which rapidly upregulates PD-L1 on most tumor cells." (PMID 39123403, 2024).
tumor (continued). "In agreement with the hypothesis that tumor-intrinsic IFNγ signaling is required for antitumor immunity, Ifngr2−/− KPAR tumors had less central memory (CD62L+CD44+) CD8+ T cells, which are important for durable antitumor immune responses." (PMID 38635884, 2024). "Another possible source of disparate IFNγ production could stem from tumor-infiltrating natural killer (NK) cells." (PMID 38565540, 2024). "Moreover, reducing intracellular K+ via overexpression of KCa3.1 can increase the production of IFNγ in T cells to inhibit tumor growth and prolong survival, which is proved in patients with head and neck cancer." (PMID 38915413, 2024). "PD-L1 expression on tumor cells is transient and relies on the production of IFNγ by TILs." (PMID 39083541, 2024). "Furthermore, T cells can release cytokines such as interferon-gamma (IFNy) and tumor necrosis factor-alpha (TNFα), which have anti-tumor effects by inducing permanent growth arrest, leading to their elimination and promotion of inflammation." (PMID 38881904, 2024). "IFNγ for example is required for tumor rejection and needs to act on the tumor vasculature." (PMID 39776913, 2024). "However, despite their presence in the TME, the T cell tumor infiltration is low and response to immune checkpoint blockade is poor, indicating that TNF and IFNγ present in the TME are insufficient to stimulate an effective anti-tumor immunity." (PMID 39723214, 2024). "We next evaluated whether IFNγ secretion from PBNP‐PTT‐derived tumor‐specific T cells corresponded with an increased cytotoxicity toward target cells." (PMID 38818122, 2024). "Additionally, a correlation between Al levels and both the presence of myeloid cells and IFNγ expression was detected, linking Al exposure to inflammatory responses within the tumor microenvironment." (PMID 39769153, 2024). "Additionally, CD4+ T cells contribute to the anti-tumor arsenal by secreting key effector cytokines, such as IFNγ and TNFα." (PMID 38892411, 2024). "A common form of intravesical therapy is BCG, and several mechanisms are thought to trigger local immune response following intravesical BCG administration, such as increased levels of urinary cytokine, elevated expression of interferon gamma, and inhibition of tumor growth." (PMID 39664392, 2024). "Notably, Pt6 tumor with an APOBEC mutator phenotype (Pt4 and Pt5 have HRD phenotype) exhibited recruitment and repression of Interferon Gamma pathways and G2M Checkpoints." (PMID 39026273, 2024). "IFNγ regulates many antitumor mechanisms in cells and can affect processes such as apoptosis of tumor cells, changing their antigenic properties, remodeling the tumor microenvironment, and improving the response to immunotherapy, and many other processes." (PMID 38396830, 2024). "Ablation of IL-33 reprograms Tregs to upregulate IFNγ expression and maintain Foxp3 expression, consistent with a “fragile” phenotype, which exhibits reduced suppressive function in vivo, thereby accelerating tumor regression." (PMID 39227959, 2024). "We demonstrated that tumor-intrinsic IFNγ signaling is critical for antitumor immunity." (PMID 38635884, 2024). "We then evaluated whether our in silico model would show the expected higher T-cell-killing efficacy of an IFNγ-induced tumor phenotype." (PMID 38636457, 2024). "or 7 × 19 CAR-T cells were cocultured with U87MG tumor, negligible levels of IFNγ were detected." (PMID 39240078, 2024). "However, the secretion of IL-17 along with other effector cytokines such as IFNγ can exert potent antitumor effects boosting tumor-specific T cell responses through enhanced dendritic and cytotoxic T cell recruitment to the tumor bed27." (PMID 38321218, 2024). "Importantly, IFNγ expression was upregulated in E.G7-OVA tumor-infiltrating Thy1.1+ CD8+ TE cells in an ARS2-dependent manner." (PMID 38233562, 2024).
tumor (continued). "Additionally, IFNγ, in conjunction with arachidonic acid, induces tumor cell ferroptosis through ACSL4, highlighting the potential of targeting tumor ferroptosis metabolism to enhance cancer immunotherapy." (PMID 39273090, 2024). "However, Granzyme A and IFNγ were markedly increased, corresponding to the increased tumor infiltration by CTLs and NK cells." (PMID 38612760, 2024). "The results of knockout experiments established that one product of ARS2-directed alternative splicing, PKM2, allows activated CD8+ T cells to fully induce glycolysis, display metabolic flexibility, produce high levels of IFNγ, and mediate efficient antigen-specific control of tumor growth in mice." (PMID 38233562, 2024). "This might be attributed to a distinct regulation of PD-L1 by environmental factors, such as IFNγ, which has been described to induce PD-L1 expression on tumor cells." (PMID 38742103, 2024). "For instance, CD8+ T cells are known to promote tumor cell ferroptosis through IFNγ secretion." (PMID 38982045, 2024). "Additionally, the overexpression of miR-148a-3p reduces the expression of PD-L1 on tumor cells induced by IFNγ and reduces T-cell apoptosis." (PMID 38462628, 2024). "However, this role seems controversial because it also showed that activated MAIT cells increased NK cell’s anti-tumor functions through IFNγ secretion." (PMID 39179536, 2024). "The ratio of IL10 to IFNγ produced by the Tr1-like cytotoxic CD4 T cells could be a key determinant in whether Tr1-like cytotoxic CD4 T cells have a net pro-tumor or anti-tumor impact." (PMID 37654482, 2023). "In contrast, IFNγ treatment resulted in a significant decrease in the growth of FAK-/- tumours." (PMID 36977556, 2023). "Another is that tumor cells are very sensitive to low levels of IFNG, therefore the effect could persist even after IFNG synthesis has substantially declined." (PMID 37182110, 2023). "Cytokines such as IFNγ and IL-2 contribute to the anti-tumor effect of PD-1 blockade." (PMID 37189417, 2023). "Therefore, we investigated the relation between EMT status, ZEB1, and PD-L1 within spatial simulations implementing scenarios with short-range IFNγ spreading at the invasive front of a tumor." (PMID 37638024, 2023). "Notably, LGG-JP significantly increases the proportion of CD8+IFNγ+ T cells, which is consistent with the tumor growth curve." (PMID 37435064, 2023). "Further, CD40 administration increased IFNγ producing T cell subpopulation, which could contribute to macrophage activation and enhanced anti‐tumor effects of CD8+ T cells." (PMID 36658712, 2023). "Interferon-gamma (IFN-γ) exerts anti-tumor effects by inducing ferroptosis." (PMID 37666810, 2023). "Moreover, DNA damage indicated by γ-H2AX staining in tumour tissues was increased by CREKA-lipo-anti-IFNγ treatment, which was inhibited by lactate treatment." (PMID 37056922, 2023). "In their study, low doses of IFNγ appeared to favor tumor growth, while high doses could eradicate NSCLC xenografts." (PMID 36839699, 2023). "Interestingly, NK cells in the tumor produced high levels of IFNγ but low levels of TNF compared to ILC1s, which correlated with antitumor activity of NK cells." (PMID 36969171, 2023). "One of the cytokines contributing to the anti-tumor response induced by PD-1 blockade is IFNγ." (PMID 37189417, 2023). "In a tumour setting, T cells become exhausted due to chronic antigen exposure leading to reduced effector function [loss of interleukin-2 (IL-2), tumour necrosis factor alpha (TNF-α) and Interferon-gamma (IFN-γ) production]." (PMID 37554723, 2023). "In fact, B-ALL cells unable to signal through the IFNγR/JAK/STAT pathway were functionally deficient for Qa-1b suggesting that the mechanism by which IF IFNγR/JAK/STAT signaling promotes CAR-T resistance is, at least in part, dependent on IFNγ-induced Qa-1b surface expression on tumor cells." (PMID 38052854, 2023).
tumor (continued). "If we demonstrate that there is a correlation in the expression of IFNγ and PD-L1 in the tumor tissue and the blood, IFNγ could be obtained from the patient’s peripheral blood by a minimally invasive method." (PMID 37509655, 2023). "A therapeutic anti-PD1 antibody could improve the killing capacity and IFNγ secretion of both Teff and Tex in a co-culture assay with PD-L1 expressing tumor cells, however, Tex functionality remained impaired." (PMID 36732507, 2023). "The role of IFNγ in tumor progression is complex and most likely time- and dose-dependent." (PMID 36980678, 2023). "As a result, they may secrete a series of immunosuppressive factors, including indoleamine 2,3-dioxygenase, TGF-β, TNFα, IFNγ, prostaglandin E2, which can help tumor cells escape from immune surveillance." (PMID 36835844, 2023). "IFNγ is an immune mediator with concomitant pro- and anti-tumor functions." (PMID 36658158, 2023). "Their study indicated that dietary tryptophan or indoles could activate the AhR of tumor-associated macrophages to reduce the accumulation of TNFα+IFNγ+CD8+ T cells, impairing the anti-tumor immune response in PDAC." (PMID 38169949, 2023). "The tumor-infiltrating IFNγ+ CD8 cells were also increased in the OXP/Pam3CSK4 group." (PMID 37945630, 2023). "Based on these findings, we concluded that IFNγ could act on the tumor cells directly and/or on host cells to indirectly control tumors via downstream effects of IFNγ." (PMID 36881506, 2023). "Since IFNG loss preceded the recovery of tumor cell proliferation, it was unclear whether IFNG signaling could completely account for the observed tumor cell-cycle arrest and what role T cell exhaustion had in these processes." (PMID 37182110, 2023). "Moreover, high production of IFNG by T cells can promote upregulation of PD-L1 in tumor cells, which will weaken the tumor response to CAR-T cells." (PMID 37122693, 2023). "However, at the same time, IFNγ potently induces upregulation of PD-L1 in tumor cells, which induces exhaustion and eventual apoptosis of tumor-infiltrating T cells." (PMID 36894639, 2023). "Depending on the cell source, IFNγ produced by T cells limits the tumor angiogenesis, while IFNγ-expressing ECs upregulate PD-L1 in tumor cells and limit antitumor immunity, which guided that multi-targeting of ANG2, VEGF, and PD-L1 enhanced antitumor responses in transplanted tumor models." (PMID 37727791, 2023). "In addition, Lenvatinib has been shown to reduce TAMs and increase IFNγ secreting CD8 effector T cells in tumor tissues in a mouse model of colon carcinoma." (PMID 37114134, 2023). "It has been reported that IFNγ secreted from T cells induces MHC class I expression on tumor cells and upregulates antigen presentation on tumor cells in the TME43; in turn, T cell expansion occurs through recognition of the antigen-MHC class I complex on tumor cells." (PMID 37258621, 2023). "Furthermore, the concentration of cytotoxic cytokines IFNγ and TNFα in tumor tissues also significantly increased in the 8FNs groups." (PMID 37162249, 2023). "To further explore this difference between MC38-L and MC38-K cells on the immunological level, we engineered T cells expressing TCRs against AdpgkR304M or Rpl18Q125R neoantigens and evaluated IFNγ secretion as well as cytotoxicity by TCR-specific T cells upon co-culture with tumor cells." (PMID 36969213, 2023). "Although MAIT cells display putative anti-tumoral functions, such as cytotoxicity and IFNγ production, it is unclear whether they may specifically recognize and target tumor cells." (PMID 37020559, 2023). "However, long-term exposure to IFNγ can exert pro-tumorigenic effects inducing immunosuppression, angiogenesis and tumor cell proliferation." (PMID 37190141, 2023). "Furthermore, FAP-positive CAFs upregulate the expression of immunosuppressive genes of MDSCs, making their ability to inhibit T-cell proliferation more effective and antagonizing anti-tumor interferon-gamma (IFNγ)+T-cell immunity." (PMID 38313431, 2023).